CRP (C-reactive protein)
Diseases named in the same sentence as CRP in open-access papers (continued):
Sharing a sentence is not in itself a finding about the gene and the disease.
rheumatoid arthritis (continued). "Resistin, an adipokine, is expressed in rheumatoid arthritis (RA) or osteoarthritis (OA) patients and in synovial joints after injury, and the plasma resistin level is significantly correlated with erythrocyte sedimentation rate (ESR) and C reactive protein (CRP)." (PMID 25264740, 2014). "Although the systemic inflammatory response that characterizes other forms of arthritis, such as rheumatoid arthritis (RA), is not usually manifest in OA, levels of the acute phase reactant C-reactive protein (CRP) have been found to be elevated in some individuals with established OA." (PMID 18312679, 2008). "Additionally, we did not evaluate various comorbidities, such as rheumatoid arthritis or pro-inflammatory markers like CRP, which could potentially influence the results." (PMID 40385578, 2025). "For example, in rheumatoid arthritis some of the principal outcome measures are worse when the patient also has FM, although objective measures of severity such as erythrocyte sedimentation rate, C reactive protein or articular erosions do not show any differences with the patients without FM." (PMID 35590317, 2022). "Assessing serological inflammation is difficult in tocilizumab (TCZ)-treated rheumatoid arthritis (RA) patients, as standard inflammation parameters, like erythrocyte sedimentation rate (ESR) and C-reactive protein (CRP), are influenced by interleukin-6-receptor inhibition." (PMID 35986420, 2022). "Since 1997, a correlation has been identified between inflammatory marker C-reactive protein (CRP) and cardiovascular risk in patients regardless of blood lipid levels, and increased risk of CVD has long been noted in patients with existing inflammatory conditions like rheumatoid arthritis (RA)." (PMID 36339576, 2022). "There is some evidence that people with rheumatoid arthritis (RA) have different colonic microbiota and that probiotic treatment can improve the condition in the absence of changes in CRP but this may not apply to our study population, most of whom likely did not have RA." (PMID 34062937, 2021). "The disease activity score 28 C-reactive protein (DAS28 CRP), rheumatoid arthritis impact of disease (RAID) score, and health assessment questionnaire (HAQ) were recorded in RA patients, and 25(OH)D serum levels were evaluated by chemiluminescent microparticle immunoassay for all subjects." (PMID 33916688, 2021). "The aim of this study was to analyze the changes in complements C3 and C4 and C-reactive protein (CRP) in patients with systemic lupus erythematosus (SLE) and rheumatoid arthritis (RA), and to evaluate the role of these indices in the differential diagnosis of SLE and RA." (PMID 24223657, 2013). "The relationship between the C-reactive protein (CRP)-albumin-lymphocyte (CALLY) index and disease activity of rheumatoid arthritis (RA) has not been explored at present." (PMID 41640573, 2026). "Inflammatory markers, such as C-reactive protein (CRP) and erythrocyte sedimentation rate, are used to monitor disease activity but are not specific to rheumatoid arthritis." (PMID 40558221, 2025). "IgM, IgG, CH50, and MMP‐3 are within the normal range, and the elevated CRP and ESR are considered to be due to the ulcer rather than the activity of rheumatoid arthritis." (PMID 40321227, 2025). "Factors that were found to be associated with disease activity in patients with rheumatoid arthritis (RA) according to the Disease Activity Score 28 (DAS28) include age, level of erythrocyte sedimentation rate (ESR), visual analog scale of pain (VAS), and C-reactive protein (CRP)." (PMID 39421133, 2024). "Disease activity score 28-C-reactive protein/erythrocyte sedimentation rate (DAS28-CRP/ESR) and Routine Assessment of Patient Index Data 3 (RAPID3) are well-known disease activity indices (DAI) that have been used to assess rheumatoid arthritis (RA) disease activity." (PMID 38361704, 2024).
rheumatoid arthritis (continued). "Serum intact PTH level in rheumatoid arthritis patients did not correlate to ESR, CRP, RF, or ACCPs in rheumatoid arthritis patients, so serum intact PTH level did not predict susceptibility to RA or disease severity according to the previous biomarkers." (PMID 37858254, 2023). "Similarly, in rheumatoid arthritis (RA) and psoriatic arthritis serum concentrations of S100A8/S100A9 are related to the inflammatory activity of arthritis, being superior to other biomarkers such as C-reactive protein and erythrocyte sedimentation rate." (PMID 37372165, 2023). "In this study, we aimed to investigate whether fibrinogen degradation products(FDP)and D-dimer could be used as serological indicators of rheumatoid arthritis(RA) activity, such as erythrocyte sedimentation rate (ESR), C-reactive protein (CRP), and platelets (PLT)." (PMID 36086781, 2022). "The level of LRG1 was also found to be correlated with CRP, erythrocyte sedimentation rate (ESR), and disease activity score 28 (DAS28), but not with the serum TNF-α levels in rheumatoid arthritis (RA)." (PMID 36569927, 2022). "In patients with rheumatoid arthritis, an autoimmune disease, LEAP-2 levels were elevated and positively correlated with C-reactive protein (CRP) and inflammatory cytokines rather than BMI." (PMID 34512549, 2021). "Inflammatory markers CRP [10.1 (3.5–20.5) vs. 3.3 (3.3–3.3), p = 0.028] but not ESR [22 (7.5–38.5) vs. 16 (10.3–20), p = 0.25] was higher in rheumatoid arthritis patients when compared to controls." (PMID 32820183, 2020). "High CRP levels are directly connected with the severity and speed of radiographic progression in males with ankylosing spondylitis (AS) and in rheumatoid arthritis (RA) patients without regard to gender." (PMID 33266394, 2020). "RA = Rheumatoid Arthritis, RF = rheumatoid factor, anti-CCP = anti cyclic citrullinated protein antibody, CRP = C-reactive protein, NA = not applicable, BMI = body mass index." (PMID 31557191, 2019). "In patients with rheumatoid arthritis, levels of s-MCAM were significantly correlated with morning stiffness, tender joint count, and swollen joint count, but not with ESR (erythrocyte sedimentation rate) or CRP (C-reactive protein) levels." (PMID 41388158, 2025). "A previous study demonstrated that the AMH level was lower in the RA group, but there was no significance of AMH levels in the activity rheumatoid arthritis, rheumatoid factor (RF), anti-cyclic citrullinated peptide (anti-CCP), erosions, C-reactive protein (CRP) level or therapeutic schedule." (PMID 37880734, 2023). "When ASOs aimed at a highly sensitive C-reactive protein (hs-CRP) were studied, they were found to have selectively reduced hs-CRP levels with a frequency of adverse reactions equal to that of the placebo group, but its utility as therapy in rheumatoid arthritis (RA) remains unclear." (PMID 33498456, 2021). "Laboratory tests typically but not invariably show increased raised inflammatory markers, such as erythrocyte sedimentation rate (ESR) and C-reactive protein (CRP), whereas rheumatoid factor (RF) and CCP antibodies are negative, in contrast to rheumatoid arthritis." (PMID 33574815, 2020). "Furthermore, the plasma levels of NT-proBNP, CRP, and TNF-α in patients with rheumatoid arthritis (RA) without clinical heart failure are higher than in control groups, suggesting that increases in the NT-proBNP levels in RA patients are related to inflammation." (PMID 28570595, 2017). "Besides, concomitant chronic diseases such as rheumatoid arthritis, systemic lupus erythematosus (SLE), and others that could possibly alter CRP levels have not been included in our registry." (PMID 36769613, 2023). "CRP was positive whereas the results of ANA and rheumatoid arthritis (RA) factor tests were negative." (PMID 31472695, 2019).
rheumatoid arthritis (continued). "Of the other 5 apps scoring ≥4/5 on the overall MARS rating (myRA, RAISE, myRAteam, Rheumatoid Arthritis Patient Companion, and RheumaTrack RA), 2 allowed entry of CRP and ESR but no other validated RA disease activity instruments were included in these apps." (PMID 28223263, 2017). "Although in these cases there are not as many optical sensors as for miRNA and C-reactive protein, the rheumatoid factor (RF) and the ACPA are widely mentioned in rheumatoid arthritis literature while histidine and IL-6 are the other two RA biomarkers covered in this section." (PMID 33158306, 2020).
heart failure (565 papers, 2006 to 2026). Inability of the heart to pump blood at an adequate rate to meet tissue metabolic requirements. "Significant change in 6MWTD, CRP level, and hierarchical composite endpoint (all-cause death, heart failure events, differences in the change in the KCCQ-CSS)." (PMID 40062142, 2025). "Long-term studies indicate that CRP is a reliable predictor of heart failure and left ventricular remodeling post-AMI, underlining its prognostic value." (PMID 40649166, 2025). "Fewer heart failure patients were observed in the higher hs-CRP quintiles, and a strong, expected association existed between fibrinogen and hs-CRP levels, as these are both inflammation biomarkers." (PMID 40004724, 2025). "Our results indicate that elevated CRP levels upon admission are correlated with a higher risk of significant adverse cardiovascular outcomes - including death, reinfarction, and heart failure - within 30 days following an AMI." (PMID 41200636, 2025). "Elevated CRP levels have been strongly associated with an increased risk of heart failure, while IL-6 and TNF-α have been implicated in the progression of ventricular dysfunction." (PMID 40787514, 2025). "Some biomarkers, such as CRP, IL-6, and IL-1β, related to aging or diseases, such as heart failure and cancer, are associated with MCI." (PMID 40281902, 2025). "Chronic inflammation, a hallmark of both frailty and heart failure, is characterized by elevated levels of proinflammatory cytokines such as interleukin-6 and C-reactive protein, which contribute to muscle wasting and functional decline." (PMID 40149736, 2025). "For example, a study showed that in patients with acute heart failure, hs-CRP levels were independently associated with an increased risk of long-term death and total heart failure admissions." (PMID 40004724, 2025). "Elevated CRP levels correlate with adverse cardiovascular outcomes, including a higher risk of heart failure." (PMID 40787514, 2025). "High CRP levels were associated with higher risk of death or heart failure hospitalization only when coexisted with high CA125." (PMID 40894478, 2025). "Current research consistently shows that elevated hs-CRP levels are associated with heart failure and worse outcomes." (PMID 40004724, 2025). "In patients with established heart failure, classical markers such as N-terminal pro-B-type natriuretic peptide (NT-proBNP), C-reactive protein, and troponin T were identified, while 421 proteins were found to be associated with prevalent heart failure." (PMID 40141349, 2025). "Increased C-reactive protein concentrations indicate systemic inflammatory processes, which have been linked to adverse outcomes in both diabetic and cardiac failure patient groups." (PMID 41573510, 2025). "This connection between CRP levels, NETosis, and heart failure provides insights into the underlying mechanisms of the disease and highlights potential therapeutic targets." (PMID 39130369, 2024). "In a systematic review that included eight anakinra clinical trials in patients with heart failure, the use of the drug was associated with a reduction in C-reactive protein (CRP) levels, indicating anti-inflammatory effects." (PMID 39184952, 2024). "Patients experiencing severe complications have higher C-reactive protein and troponin T level, the severity of cardiovascular complications like heart rate variability and heart failure following virus infection associated with elevated CRP." (PMID 38706946, 2024). "In the STEP-HFpEF trial, semaglutide use in obese heart failure patients with preserved LVEF was associated with a significant reduction in CRP levels, indicating a potential decrease in inflammation, a key factor in the development and progression of HFpEF." (PMID 39462311, 2024). "CRP levels have been confirmed to be associated with prognosis in patients with heart failure, atherosclerotic disease, myocarditis and atrial fibrillation, and CRP itself is toxic to the myocardium." (PMID 38233747, 2024).
heart failure (continued). "Several recent studies have demonstrated that the concentrationof CRP is a strong predictor of the occurrence or exacerbation of heart failureevents in both patients with heart failure and high-risk populations." (PMID 39742221, 2024). "Traditional observational studies have shown positive associations between c-reactive protein (CRP) and heart failure (HF) risk." (PMID 36882679, 2023). "All-cause mortality was found to be related to heart failure, chronic pulmonary disease shock, and C-reactive protein levels." (PMID 36811731, 2023). "In a multivariate logistic regression, factors associated with a higher risk of death were age >65 years, glycaemia >10 mmol/L, CRP and D-dimer level, prehospital insulin and loop diuretic use, presence of heart failure, and chronic kidney disease." (PMID 36844106, 2023). "ROC analysis showed that CRP levels >5 mg/L effectively predicted postoperative heart failure, and NLR >3.5 had a good predictive effect on all-cause mortality within 30 days after surgery." (PMID 37063874, 2023). "Contrary to our findings, they were unable to establish a causal relationship between CRP and heart failure risk." (PMID 36882679, 2023). "Using two-sample Mendelian randomization, we found that genetically determined CRP was causally associated with the risk of heart failure in the European population." (PMID 36882679, 2023). "Authors have previously found a relationship between the severity of OS and the New York Heart Association (NYHA) functional class, hs-CRP levels and proBNP in patients with heart failure." (PMID 37646033, 2023). "Briefly, our analysis offers evidence that CRP, a risk factor, plays a significant role in the development of heart failure." (PMID 36882679, 2023). "In summary, our findings provide genetic support for a potential causal relationship between c-reactive protein and heart failure." (PMID 36882679, 2023). "The literature has demonstrated that high CRP levels are associated with diastolic dysfunction and heart failure risk." (PMID 36059561, 2022). "Early clinical reports dating back to the 1950s on an association of C-reactive protein (CRP) with different etiologies of heart failure began to suggest inflammation as an important component to the condition." (PMID 36382160, 2022). "Increased CRP values (>3 mg/L) have also been identified as predictors of heart failure and its severity in high-risk populations." (PMID 35203703, 2022). "High C-reactive protein (CRP) levels are associated with poor outcomes of heart failure (HF), and statins are known to reduce CRP levels." (PMID 36620625, 2022). "After adjustment for established risk factors (age, NIHSS, heart failure, atrial fibrillation, and C reactive protein), SIRT6 levels were negatively associated with mortality." (PMID 36443316, 2022). "Nevertheless, the prognostic and diagnostic value of CRP required further investigation in geriatric hip fracture patients with perioperative heart failure." (PMID 35067910, 2022). "They found that participants with higher hs-CRP levels also had an independently increased risk of incidental heart failure and all-cause death than those with lower hs-CRP levels." (PMID 34356982, 2021). "Emerging biomarkers which have been introduced in association with increased CV risk and mortality include markers of inflammation, heart failure or kidney dysfunction, e.g. CRP, Brain Natriuretic Peptide (BNP) and cystatin C29–33." (PMID 34083628, 2021). "Our results showed the same result in that the downregulated gene SMAD4 in MI samples was implicated in heart failure and low CRP value." (PMID 33224271, 2020). "The primary endpoint, including a significant reduction of cardiovascular death, remained unmet, but in patients with a STEMI with higher age, elevated hs-CRP or chronic kidney disease, the risk of heart failure tended to be reduced." (PMID 33344515, 2020).